MT1JP (metallothionein 1J, pseudogene)
Diseases named in the same sentence as MT1JP in open-access papers (continued):
Sharing a sentence is not in itself a finding about the gene and the disease.
tumor (27 papers, 2016 to 2025). "This indicates that MT1JP exerts its tumor-suppressing effects in ICC by regulating the miR-18a-5p/FBP1 axis." (PMID 39458127, 2024). "Functionally, overexpression of MT1JP was found to inhibit cell proliferation, migration and invasion, promote cell apoptosis in vitro and slow down tumor growth and metastasis in vivo." (PMID 35270630, 2022). "In retinoblastoma, MT1JP plays a tumor suppressive role via targeting Wnt/β-catenin signaling pathway." (PMID 35928868, 2022). "For example, LncRNA MT1JP can suppress cell growth, migration, and invasion, promote cell apoptosis in vitro, and inhibit tumor growth and metastasis in vivo." (PMID 34307360, 2021). "LncRNA metallothionein 1 J, pseudogene (MT1JP) has been reported to play tumor-suppressing roles in multiple cancers." (PMID 33557774, 2021). "Further, hsa-miR-532-3p along with hsa-miR-139 are associated with CHRD, FLAD1, MT1JP, and EBF2 in our analysis and have been identified as tumor suppressors in HCC that inhibit cell proliferation, migration, and invasion." (PMID 32228601, 2020). "Functionally, overexpression of lncRNA MT1JP inhibited cell proliferation, migration, invasion and promoted cell apoptosis in vitro, and inhibited tumor growth and metastasis in vivo." (PMID 29720189, 2018). "One recent study implied that the lncRNA MT1JP played a potential role in promoting apoptosis to restrain the growth of tumour cells." (PMID 27966580, 2016). "Together, our results suggest that MT1JP is a novel tumor suppressor, and broaden our knowledge of the development of human tumors." (PMID 26909858, 2016). "We found that MT1JP is differentially expressed in tumor tissues by analyzing data from a customized microarray applied to 76 pairs of matched normal and cancer tissue samples." (PMID 26909858, 2016). "In the present study, we report a lncRNA named MT1JP which acts as a tumor suppressor through a posttranscriptional mechanism." (PMID 26909858, 2016). "Our data show that MT1JP has considerably lower expression in tumor tissue samples than in matched normal tissue ones, which was observed among samples from gaster, colon, liver and lung." (PMID 26909858, 2016). "In line with the microarray analysis, we found that MT1JP had considerably lower expression in almost all tumor samples." (PMID 26909858, 2016). "To further investigate the effects of MT1JP on tumor inhibition, we constructed a plasmid for overexpression of MT1JP in HepG2 and SMMC-7721 cells, which normally express MT1JP at lower levels than L02 cells." (PMID 26909858, 2016). "In vivo data revealed that lncRNA MT1JP reduced tumor sizes and tumor metastasis." (PMID 35928868, 2022).
tumor (continued). "Bi et al28 showed the putative tumor‐suppressor role of MT1JP by negatively modulating the action of the Wnt/β‐catenin signaling pathway in the development of RB and that it may also be used as a prognostic biomarker and therapeutic target." (PMID 31038819, 2019). "To address whether MT1JP exert its effects as a tumor suppressor, we first investigated in more detail the role of MT1JP in tumor suppression." (PMID 26909858, 2016). "Since MT1JP may have a role as a tumor suppressor in several kinds of cancers, it is likely that the translational regulation by the MT1JP protein complex demonstrated in this study is a widely occurring tumor suppression phenomenon." (PMID 26909858, 2016). "More generally, its consistent expression pattern in numerous tumor specimens indicates that MT1JP may be a significant biomarker of diagnosis with a potential in cancer therapy." (PMID 26909858, 2016). "Similarly, the LncRNA MT1JP inhibits tumor growth by negatively regulating the Wnt/β‐catenin signaling pathway, suggesting that MT1JP may serve as a prognostic biomarker and therapeutic target." (PMID 35592755, 2022). "MT1JP adsorbs miR-92a-3p to target and regulate the expression of FBXW7, which is a tumor suppressor molecule that plays an important role in tumor apoptosis, epithelial cell differentiation, and drug resistance in GC." (PMID 39210921, 2024). "In summary, our study confirmed the anti-tumor effect of MT1JP on TNBC, and MT1JP inhibited the progression of TNBC possibly by upregulating miR-138 and inhibiting HIF-1α." (PMID 35703312, 2022). "Except for MT1JP and BDNF-AS, which are down-regulated and act as a tumor suppressor gene in RB, other lncRNAs are all up-regulated in RB and promote RB progression." (PMID 30905893, 2019). "We analyzed the expression and function of MT1JP in TNBC and found that MT1JP was downregulated in TNBC and may play a tumor suppressive role by upregulating miR-138, which can direct target HIF-1α." (PMID 35703312, 2022). "In ICC, several lncRNAs such as lncRNA MT1JP and lncRNA AGAP2-AS1 have been shown to exhibit their tumor-related effects via sponging miRNAs to modulate the expression of various genes involved in tumor progression." (PMID 34239888, 2021). "In line with in vitro analysis, the results indicated that the volume and weight of xenograft tumor were significantly lower in MT1JP overexpression group as compared with negative control group." (PMID 29720189, 2018). "We further identified a significant positive correlation between MT1JP and the expression of miR-138, and a significant negative correlation between MT1JP and the expression of HIF-1α in tumor tissues." (PMID 35703312, 2022). "Furthermore, knockdown of MT1JP resulted in a range of changes which usually arise during tumor formation, including cell cycle arrest, apoptosis inhibition, proliferation acceleration, and increased invasion and migration, as opposed to the effects of MT1JP overexpression." (PMID 26909858, 2016).
cancer (8 papers, 2016 to 2023). A tumor composed of atypical neoplastic, often pleomorphic cells that invade other tissues. "MT1JP, a down-regulated lncRNA in GC, was associated with malignant tumor phenotypes and survival of GC." (PMID 29720189, 2018). "Down- or up-regulation of MT1JP led to variation in the expression of numerous cancer-associated mRNA molecules." (PMID 26909858, 2016). "Even more importantly, the association between MT1JP and RNA-binding protein provides a novel node in the complicated cancer regulatory network." (PMID 26909858, 2016). "The survival time was significantly lengthened in cancer patients with a higher expression level of MT1JP." (PMID 35270630, 2022). "A previous study has extensively investigated the expression of MT1JP in cancers developed from four types of organ." (PMID 35703312, 2022). "The MT1JP was decreased and miR-18a-5p was increased in intrahepatic cholangiocarnoma tissues, compared with para-carcinoma tissues, which was consistence with data from TCGA database." (PMID 33557774, 2021). "We validate our analysis via the public dataset and also sum up the studies of lncRNA BDNF-AS and MT1JP in other cancers." (PMID 32514246, 2020). "In order to select one or more cell lines for functional studies of this lncRNA, we examined the MT1JP expression in several cell lines derived from normal or cancer cells of three kinds of tissues." (PMID 26909858, 2016). "LncRNA, Metallothionein 1 J, pseudogene (MT1JP), may suppress cancer cell proliferation and migration by transcriptionally activating miR-138, which directly targets HIF1α mRNA transcripts." (PMID 37583933, 2023). "To investigate which pathway MT1JP might be involved in, we conducted a Gene Ontology (GO) analysis of genes whose expression was strongly correlated (r2 > 0.25) to that of MT1JP in the normal and matched cancer tissues." (PMID 26909858, 2016).
infection (1 paper, 2016). The state of being infected such as from the introduction of a foreign agent such as serum, vaccine, antigenic substance or organism. "In our microarray data, the expression of MT1JP in macrophages with H37Ra infection was significantly higher than that with H37Rv infection." (PMID 27966580, 2016).
MT1JP also shares sentences with these, for which no sentence is quoted: hepatocellular carcinoma (3 papers); glioblastoma (1).